BRAF (B-Raf proto-oncogene, serine/threonine kinase)
Diseases named in the same sentence as BRAF in open-access papers (continued):
Sharing a sentence is not in itself a finding about the gene and the disease.
metastatic melanoma (continued). "Currently, it is more often used as combination therapy with BRAF inhibitors for the treatment of unresectable or metastatic melanoma harboring BRAF V600E and/or V600K mutation." (PMID 38239196, 2023). "The assessment of BRAF mutational status is also currently considered in metastatic melanoma diagnosis." (PMID 36835424, 2023). "A 51-year old female patient with metastatic melanoma from TCGA cohort (TCGA-EE-A29T) was found to have a somatic oncogenic BRAF mutation." (PMID 37207338, 2023). "Recently, encorafenib in combination with binimetinib, a MEK inhibitor, was approved by the FDA for the treatment of patients with unresectable or metastatic melanoma with BRAF V600E or V600K mutations, based on findings from the COLUMBUS trial." (PMID 37834222, 2023). "In metastatic melanoma patients who lack BRAF V600E mutations (including patients with NRAS and NF1 mutation), targeted therapy has shown minimal effectiveness." (PMID 37444637, 2023). "BRAF inhibitors have improved the treatment of advanced or metastatic melanoma in patients that harbor a BRAFT1799A mutation." (PMID 37446932, 2023). "Further in the list, Cobimetinib/GDC-0973 is FDA-approved for the treatment of patients with metastatic melanoma with a BRAF V600E or V600K mutation, in combination with vemurafenib." (PMID 37993971, 2023). "Anti-BRAF therapies are associated with significantly improved OS in patients with metastatic melanoma and the BRAF V600E mutation." (PMID 37649946, 2023). "The use of specific inhibitors towards mutant BRAF (BRAFi) and MEK (MEKi) in BRAF-mutated patients has significantly improved progression-free and overall survival of metastatic melanoma patients." (PMID 37372043, 2023). "Biopsy confirmed metastatic melanoma positive for a pathogenic variant in codon 600 of the BRAF gene (c.1799 T > A, p.Val600Glu)." (PMID 36604647, 2023). "In comparison to anti-CTLA-4, Pembrolizumab, Nivolumab, and anti-PD-1 antibodies which are associated with increased viability of patient with metastatic melanoma, the Ipilimumab is on first stage of wild melanoma treatment with metastatic BRAF." (PMID 37605149, 2023). "Approximately 50% of patients with metastatic melanoma harbor somatic mutations in the B-Raf proto-oncogene (BRAF), which leads to constitutive activation of the BRAF oncoprotein." (PMID 36674809, 2023). "Cobimetinib is FDA-approved to treat BRAF-mutated metastatic melanoma in combination with vemurafenib." (PMID 37359725, 2023). "In metastatic melanoma patients, ctDNA detection promotes the identification of typical mutations (i.e., BRAF and Neuroblastoma RAS Viral Oncogene Homolog (NRAS)) and epigenetic markers such as methylated DNA." (PMID 36835424, 2023). "In 2011, the FDA approved vemurafenib, a selective oral BRAF-mutant inhibitor, for the treatment of unresectable or metastatic melanomas harbouring activated BRAFV600E mutations, as identified by Davies." (PMID 37175742, 2023). "In particular, the combination of BRAF and MEK inhibitors has been shown to be effective in patients with metastatic melanoma harboring BRAF mutations." (PMID 36831463, 2023). "Cobimetinib and binimetinib were granted FDA approval also as combination therapy with BRAF inhibitors for the treatment of patients with unresectable or metastatic melanoma with BRAF V600E/V600K mutation." (PMID 38239196, 2023). "The analysis of BRAF and C-KIT mutations was performed in 43% of cases of metastatic melanoma and revealed BRAF V600E mutation in six cases and C-KIT mutation in five cases." (PMID 37649946, 2023). "This led to the regulatory approval of vemurafenib, dabrafenib and encorafenib (and combinations with MEK inhibitors and other agents) for the treatment of patients with unresectable or metastatic melanoma harboring a BRAF V600E mutation." (PMID 37219686, 2023).
metastatic melanoma (continued). "BRAF V600 mutations are present in about 50% (43–66%) of primary or metastatic melanoma, thus the rate of 42% BRAF V600 mutated tumors in our study corresponds very well to the literature." (PMID 35192052, 2023). "Namely, we investigated the question of the optimal second line treatment in metastatic melanoma patients bearing an actionable BRAF V600 mutation and progressing after a first line of immunotherapy." (PMID 37025593, 2023). "In the clinical setting, the recommended dose of Vemurafenib for treating metastatic melanoma with BRAF (V600E) mutation is 960 mg twice daily." (PMID 37620300, 2023). "Dabrafenib is a potent inhibitor for mutated BRAF that is currently being utilized as the first or subsequent line treatment for patients with unresectable or metastatic melanoma with BRAF V600 mutations." (PMID 37834222, 2023). "Atezolizumab (anti-PD-L1), an FDA-approved mAbs, was recommended for use in combination with the BRAF inhibitors cobimetinib and vemurafenib to treat metastatic melanoma that has the BRAF V600 mutation." (PMID 37525217, 2023). "There are a variety of gene mutations that can lead to metastatic melanomas, the most common one being the BRAF mutation (40%)." (PMID 36838864, 2023). "Both dabrafenib and vemurafenib monotherapy as well as dabrafenib/trametinib and vemurafenib/cobimetinib combination therapies are approved indications for unresectable stage III or metastatic melanoma that is BRAF V600E–mutated." (PMID 37124503, 2023). "For example, in an open-label, multicentre study of patients with BRAF mutated metastatic melanoma treated with vemurafenib, only 90 (3.3%) patients endured CR, and 829 (30.6%) patients endured PR." (PMID 37919738, 2023). "Case presentation: We reported a case of a 64-year-old female metastatic melanoma patient with a novel BRAF p.L485-P490 deletion mutation." (PMID 36686670, 2023). "Resistance to therapies is a major challenge in the management of BRAF-mutated metastatic melanoma treated with BRAFi and MEKi." (PMID 37296851, 2023). "The FDA has approved BRAF inhibitors (vemurafenib, dabrafenib) and MEK inhibitors (trametinib, cobimetinib) for the treatment of metastatic melanoma harboring BRAF mutations." (PMID 37568654, 2023). "Before 2017, the keywords that popped up were individual, mice, of the literature, vemurafenib, ras mutation, metastatic melanoma, dabrafenib, Raf inhibitor, tissue, BRAF inhibitor and braf are mostly related to mechanism therapy and prognosis." (PMID 37114133, 2023). "Several studies have shown ctDNA fluctuations in different tumor contexts, such as in pancreatic cancer and BRAF-mutated metastatic melanoma." (PMID 36835424, 2023). "In 2011, vemurafenib was approved for patients with advanced metastatic melanoma with the BRAF V600E mutation using FDA." (PMID 36551302, 2022). "Trametinib as monotherapy was shown to improve OS and PFS in comparison with standard dacarbazine or paclitaxel chemotherapy among patients with BRAF V600E or V600K mutated metastatic melanoma." (PMID 35130943, 2022). "After 2014, BRAF–MEK inhibitor combinations were considered the standard of care for BRAF-mutated metastatic melanoma, extending median PFS and OS to approximately 12 and 24 months, respectively." (PMID 35453572, 2022). "The response rate to BRAF and MEK inhibitors in metastatic melanoma patients with the BRAF V600 mutation is ca. 70% in selected patients, with less than 10% of patients having the highest response to progressive disease." (PMID 36613491, 2022). "TRIAL 2 evaluated the use of vemurafenib 960 mg twice a day in 132 patients previously treated with systemic therapy for metastatic melanoma BRAF V600E mutated." (PMID 35742834, 2022). "We present a case of metastatic melanoma that was treated in an emergent setting using therapy supported by rapid PCR-based detection of ctDNA positive for a BRAF V600 mutation." (PMID 35756682, 2022).
metastatic melanoma (continued). "Dabrafenib (GSK2118436) is a selective BRAFi that was approved in 2013 by the FDA as a single agent for the treatment of unresectable or metastatic melanoma in patients with the BRAF V600E mutation." (PMID 36358912, 2022). "Mutated BRAF inhibitors dabrafenib and vemurafenib were approved for treating BRAF(V600E) metastatic melanoma." (PMID 36145516, 2022). "Promising results from the phase II clinical trial of triplet combination of nivolumab with dabrafenib and trametinib (TRIDeNT) in patients with PD1 naïve or refractory BRAF-mutated metastatic melanoma have also been published." (PMID 36358912, 2022). "Testing for the BRAF mutation is mandatory for the management of patients with locally advanced or metastatic melanoma." (PMID 35328303, 2022). "She underwent surgical stabilization of the fracture, and a biopsy of the bone lesion revealed metastatic malignant melanoma with BRAF V600E mutation." (PMID 35308763, 2022). "In patients with metastatic melanoma with a BRAF mutation, BRAF/MEK inhibitors can modify the immune profile." (PMID 35203494, 2022). "A study from Ontario, Canada found that among patients with metastatic melanoma who were tested for BRAF mutation, more than one-third (38.3%) tested positive." (PMID 35323369, 2022). "Metastatic melanoma presents, in many cases, oncogenic mutations in BRAF, a MAPK involved in proliferation of tumour cells." (PMID 36726591, 2022). "The efficacy of the combination of BRAF and mitogen-activated protein kinase/extracellular signal-regulated kinase kinase inhibitors has been reported in patients with BRAF-mutated metastatic melanoma." (PMID 37082097, 2022). "The use of dabrafenib 150 mg twice a day was also evaluated in metastatic melanoma BRAF V600E mutated with brain metastasis." (PMID 35742834, 2022). "The approval was based on a phase 3 randomized, active-controlled, open-label, multicentre trial (COLUMBUS), that enrolled 577 BRAF-mutated patients with unresectable or metastatic melanoma." (PMID 36230797, 2022). "Dabrafenib inhibits the cell proliferation of metastatic melanoma with the oncogenic BRAF(V600)-mutation." (PMID 35214043, 2022). "Regarding CD163, a recent study reported that the activation of effector T cells and the depletion of macrophages 163+ in the tumour are associated with a good response to BRAF inhibitor treatment in patients with metastatic melanoma." (PMID 35203494, 2022). "In another study, patients are being recruited to determine the efficacy of combinations of nilotinib with dabrafenib/trametinib in metastatic melanoma patients with BRAF mutations [NCT04903119]." (PMID 35954441, 2022). "Retrospective data of a cohort of 58 patients with metastatic melanoma harboring a BRAF V600 mutation other than V600E/K revealed a response to MAPK inhibition in 45% [13••]." (PMID 35380338, 2022). "In order to identify the best treatment choice in BRAF-mutated metastatic melanoma patients, we conduct a comparison between treatments." (PMID 36046043, 2022). "To date, there is a debate about which is the most appropriate first-line treatment choice in BRAF-mutated metastatic melanoma." (PMID 36046043, 2022). "Conversely to our TCGA analysis, the BRAF-mutated A375M showed an elevated expression of ERα, thus representing a model of metastatic melanoma, opposite to the NRAS ones in our study." (PMID 35371312, 2022). "In phase III clinical trials, comparison of vemurafenib with dacarbazine for the treatment of BRAF V600E-mutated metastatic melanoma showed that vemurafenib was associated with a 74% reduction in the risk of death or disease progression." (PMID 35954441, 2022). "Treatment of metastatic melanoma includes the option of targeted therapy in patients with driver BRAF mutations." (PMID 35756682, 2022). "Currently, there are several studies that establish BRAF-targeted therapy as standard treatment for patients with metastatic melanoma who carry a BRAF mutation." (PMID 36143339, 2022).
metastatic melanoma (continued). "All of these drugs are approved for the treatment of unresectable or metastatic malignant melanoma with the BRAF V600 mutation." (PMID 35406444, 2022). "In particular, several studies conducted on metastatic melanoma patients have highlighted the utility of liquid biopsy in detecting and monitoring BRAF/NRAS mutations through the use of different technologies." (PMID 35804825, 2022). "At the same time, in a recent meta-analysis, the presence of a BRAF mutation was shown to be statistically significantly associated with reduced overall survival (OS) in metastatic melanoma patients." (PMID 35456332, 2022). "In 2011 the first BRAF inhibitor was approved for metastatic melanoma patients with BRAF V600E/K mutated tumors, which would be followed by combination BRAF and MEK inhibition therapy." (PMID 35274007, 2022). "In 2018, the FDA approved the combination of encorafenib and binimetinib (an anti-MEK1/2 protein kinase inhibitor) for the treatment of patients with unresectable or metastatic melanoma with a BRAF V600E or V600K mutation." (PMID 36230797, 2022). "In a preclinical model of BRAF(V600)-mutated metastatic melanoma, anti­PD1 therapy in combination with BRAF and MEK inhibitors contributed to complete tumor regression with increasing T-cell infiltration into tumors." (PMID 36189283, 2022). "Recent phase III clinical trial findings showed that encorafenib monotherapy was more effective than vemurafenib in the treatment of BRAF-mutated metastatic melanoma." (PMID 35954441, 2022). "Two BRAF inhibitors, vemurafenib and dabrafenib, are approved in the United States and Europe for treatment of patients with unresectable or metastatic melanoma with BRAF V600E mutations and function as small molecule inhibitors of BRAF kinase." (PMID 35626272, 2022). "Clinical studies indicated that a combination of dabrafenib and trametinib, compared with dabrafenib alone, improved the 16% overall response rate in previously untreated patients who had metastatic melanoma with BRAF V600E or V600K mutations." (PMID 36551302, 2022). "We included 249 patients with metastatic melanoma treated in our institution between 2014 and 2021; the median age was 62 years (range: 17–90); 58% were males, and 37% of patients had the BRAF mutation." (PMID 35267557, 2022). "Clinical studies show trametinib, an MEK inhibitor, improved rates of progression-free and overall survival among patients who had metastatic melanoma with a BRAF mutation compared with chemotherapy." (PMID 36551302, 2022). "Based on these results, atezolizumab has been granted approval for use in combination with cobimetinib and vemurafenib for patients with BRAF V600 mutation-positive unresectable or metastatic melanoma." (PMID 36358912, 2022). "The FDA and the European Medicines Agency (EMA) have approved the targeted drug for treating patients with unresectable or advanced metastatic melanoma with BRAF V600E mutation." (PMID 36612173, 2022). "Encorafenib is a kinase inhibitor, approved for the management of unresectable or metastatic melanoma with BRAF V600E or BRAF V600K mutation at the dosage of 450 mg (six 75 mg capsules) once a day in combination with binimetinib 45 mg twice a day." (PMID 35742834, 2022). "Treatment beyond frontline therapy for patients with BRAF-mutated advanced/metastatic melanoma is currently under investigation in prospective trials." (PMID 35565255, 2022). "Compared to chemotherapy, BRAF inhibitors improve clinical response rates, progression-free survival, and overall survival in metastatic melanoma patients with BRAF mutations." (PMID 35326683, 2022). "The FDA‐approved course of treatment for metastatic melanoma patients with BRAF mutations are BRAF inhibitors, which inhibits the BRAF kinase and blocks signaling to the MAPK/ERK pathway." (PMID 35044091, 2022).
metastatic melanoma (continued). "The combinations vemurafenib-cobimetinib, dabrafenib-trametinib and encorafenib-binimetinib constitute the first line of treatment for patients with BRAF-mutated metastatic melanoma." (PMID 36143339, 2022). "The efficacy and safety of nivolumab in previously treated (ipilimumab and BRAF inhibitor, if BRAF V600 mutation was positive) metastatic melanoma was evaluated in a multicenter, randomized (2:1) trial (CHECKMATE-037), which enrolled 450 subjects." (PMID 35742834, 2022). "Preclinical models suggest that combining BRAF and MEK inhibitors with PD-1 blockade therapy was of benefit to a subset of patients with BRAF(V600)-mutated metastatic melanoma." (PMID 36551302, 2022). "Its efficacy has been evaluated in a randomized-controlled trial (TRIAL 1) involving 675 patients with unresectable or metastatic melanoma BRAF V600E mutation-positive receiving vemurafenib 960 mg twice a day or dacarbazine." (PMID 35742834, 2022). "Recently, study of the efficacy and safety of nivolumab in 440 patients with wild-type BRAF and mutant BRAF metastatic melanoma showed that nivolumab administration caused improved ORR regardless of the PD-L1 status of the tumor." (PMID 34980128, 2022). "The most prevalent BRAF mutation is the V600E mutation, especially in metastatic melanoma, where 70%–90% of patients express this specific point mutation." (PMID 35044091, 2022). "This phenomenon has been previously suggested for dabrafenib in BRAF-mutated metastatic melanoma patients." (PMID 36145591, 2022). "There are different FDA-approved BRAF inhibitors for patients with BRAF V600 mutations in metastatic melanoma resulting in a significant overall survival benefit, although half of the patients showed resistance." (PMID 35326682, 2022). "Another relevant contribution deriving from RWD was the demonstration of lower efficacy of immunotherapy in BRAF-mutated metastatic melanoma patients relapsing on MAPK inhibition compared with MAPKi naïve patients." (PMID 35814399, 2022). "Vemurafenib was the first BRAF kinase inhibitor approved (by the FDA in 2011) for the treatment of metastatic melanoma patients with the BRAF V600E mutation." (PMID 36699049, 2022). "In patients with unresectable metastatic melanoma harboring a BRAF V600E mutation, vemurafenib, a BRAF inhibitor, afforded a higher response rate and longer progression-free survival and overall survival than chemotherapy with dacarbazine." (PMID 36230564, 2022). "In 2013, the first MEK1/2 inhibitor, trametinib, was approved for BRAF-mutated metastatic melanoma after demonstrating improved PFS and OS compared to dacarbazine." (PMID 35453572, 2022). "MEK inhibitors are approved by the US Food and Drug Administration for use in combination with BRAF inhibitors for the treatment of metastatic melanoma harboring BRAF V600E/K mutation." (PMID 35075200, 2022). "In metastatic melanoma, a well-characterized predictive biomarker of response guiding the therapeutic decision process is the BRAF V600 mutation, which is somehow predictive of response to BRAF ± MEK inhibition with low rates of primary resistance." (PMID 36613491, 2022). "Dabrafenib and trametinib are two available molecules that have been approved for the treatment of metastatic melanoma with BRAF-V600E or V600K mutations." (PMID 35454350, 2022). "Trametinib is an inhibitor of MEK and was developed to treat BRAF-mutated metastatic melanoma by targeting MEK." (PMID 36699049, 2022). "To date, one of the reference therapies for the treatment of mutated BRAF metastatic melanoma is based on the combination of BRAF and MEK inhibitors." (PMID 36612138, 2022). "In 2011, almost a decade after the seminal BRAF mutation discovery, vemurafenib became the first selective BRAF inhibitor to be approved by the FDA as metastatic melanoma monotherapy." (PMID 35453572, 2022).